BRCA2 (BRCA2 DNA repair associated)
Diseases named in the same sentence as BRCA2 in open-access papers (continued):
Sharing a sentence is not in itself a finding about the gene and the disease.
breast cancer (continued). "Individuals carrying BRCA1 or BRCA2 mutations, associated with elevated breast cancer risk, often opt for risk-reducing mastectomies, significantly diminishing the likelihood of future breast cancer occurrences." (PMID 38674216, 2024). "The susceptibility genes BRCA1 (breast cancer 1) and BRCA2 (breast cancer 2) are critical in the DNA damage response (DDR)." (PMID 39272660, 2024). "Having a close blood relative with a history of breast cancer and the presence of inherited mutations in genes like the BReast CAncer genes 1 (BRCA1) and 2 (BRCA2) raises breast cancer risk in approximately 5%–10% of women." (PMID 38807767, 2024). "BRCA1 and BRCA2 are high-penetrance breast cancer predisposition genes that were identified in the 1990s by genome-wide linkage analysis and positional cloning." (PMID 39438962, 2024). "BRCA1 and BRCA2 genes are significant markers for increased breast cancer risk, with mutations in these genes associated with a higher likelihood of developing breast and ovarian cancers." (PMID 38516286, 2024). "We conclude that BRCA1-associated breast cancer has a higher rate of overall and nodal pCR than both BRCA2-associated and sporadic disease." (PMID 39060255, 2024). "Local association study with Fisher’s test (Bonferroni-corrected significance threshold 0.05/8,268 = 6.05 × 10−6) was performed ‘re-discovering’ BRCA1 and BRCA2 as breast cancer susceptibility genes." (PMID 38200129, 2024). "For example, Ashkenazi Jewish women have a higher prevalence of BRCA1 and BRCA2 mutations, which significantly increase their risk of developing breast cancer." (PMID 39507494, 2024). "For analysis examining a BRCA2 variant in unselected breast cancer cases versus controls, a target OR≥4 is appropriate." (PMID 39227160, 2024). "Breast cancer survivors who carry a BRCA1 or BRCA2 gene mutation are at high risk of cancer recurrence." (PMID 39192282, 2024). "The ATM missense variant c.7271T > G, initially associated with a milder phenotype of ataxia-telangiectasia (A-T), has been found to carry a substantial breast cancer risk comparable to that of BRCA2." (PMID 38397209, 2024). "BRCA mutations (BRCA1 or BRCA2), which affect approximately 3–5% of breast cancer patients, are clinically significant in treatment decisions." (PMID 39484212, 2024). "Recently, a phenotype suggesting more aggressive tumor behavior has been associated with BRCA2 male breast cancer." (PMID 38472501, 2024). "In BRCA2 carriers, the 20-year contralateral breast cancer risk is 26% but also ranges from 20 to 68% depending on one’s age at the time of index breast cancer." (PMID 38248108, 2024). "The prevalence of pathogenic variants in the specific genes BRCA1 and BRCA2 in unselected breast cancer patients has been estimated to be 2–2.5%, similarly to what has been reported in the Southern Swedish population." (PMID 38491334, 2024). "It is possible that enhanced plasticity of BRCA1-mutant epithelial cells make these cells more susceptible to basal-like breast cancers, whereas limited plasticity makes tumors in BRCA2 mutation carriers similar to sporadic breast cancers." (PMID 38059556, 2024). "BRCA1 and BRCA2 are tumor suppressor genes whose mutations have been historically associated with an increased lifetime risk of developing breast cancer (50 -80%) and ovarian cancer (30 - 50%)." (PMID 39314634, 2024). "Data on real-world prevalence and outcomes in patients diagnosed with pathogenic germline variants in BRCA1 or BRCA2 (gBRCAm) breast cancer is sparse." (PMID 39319938, 2024). "Among these, mutations in the BRCA1 and BRCA2 genes have a particularly important role in the development of breast cancer." (PMID 39192282, 2024). "Triple-negative breast cancer is prevalent in BRCA1 mutation carriers, whereas estrogen receptor-positive, HER2-negative luminal breast cancer is more common in BRCA2 mutation carriers." (PMID 39174799, 2024).
breast cancer (continued). "Inhibition of EZH2 in a mouse BRCA2−/− breast cancer model is associated with acquired PARPi resistance." (PMID 37588193, 2024). "A case of simultaneous prostate cancer and breast cancer in an individual with a BRCA2 mutation has been reported previously, but a case of simultaneous familial breast cancer and prostate cancer has not." (PMID 39364320, 2024). "We hereby present the acute toxicities of locoregional breast radiation therapy with concurrent olaparib in a patient treated for BRCA2-mutated breast cancer." (PMID 38799106, 2024). "Specific activation of PDK1 in BRCA2 mutation carriers is interesting as this kinase has recently been shown to confer resistance to CDK4/6 inhibitors in ER+ breast cancer cell lines, and inhibitors targeting this kinase are under development." (PMID 38059556, 2024). "Although a number of high-risk breast cancer genes have been identified, including BRCA1 and BRCA2, the risk profile of many high-risk families cannot be explained using known breast cancer genes." (PMID 38397208, 2024). "Most of the 28 patients who underwent quadrantectomy in combination with other surgical procedures corresponded to inherited breast cancer cases with PVs in associated genes (71.4%; 20/28), mainly BRCA2 (9/20; 45%) and BRCA1 (7/20; 35%)." (PMID 38893140, 2024). "One year of adjuvant olaparib is currently indicated either alone or concurrently with endocrine therapy in early breast cancer with BRCA1- or BRCA2-mutated high-risk patients that have received local treatment and neoadjuvant or adjuvant chemotherapy." (PMID 38869741, 2024). "In 2009, the first clinical trial of the PARPi demonstrated a synthetic lethal for olaparib in breast cancer with BRCA1/BRCA2 deficiency." (PMID 37588193, 2024). "Then, we focused on deleterious mutations of BRCA1 and BRCA2, the most crucial genes increasing the risk of ovarian and breast cancer." (PMID 38509102, 2024). "The most common pathogenic variant of the BRCA1 and BRCA2 in breast cancer patients was c.2635G > T and c.5164_5165del, respectively." (PMID 38167124, 2024). "Given the contrasting correlation of MLH1 expression with colon versus breast cancer survival probability and the observation that most BRCA2 mutation carriers develop ERα-positive (ER+) breast cancer, we investigated MLH1 expression in breast tissues." (PMID 38271119, 2024). "Resveratrol is a phytoestrogen that binds to estrogen receptors and activates them, controlling the transcription of estrogen-responsive target genes including BRCA1 and BRCA2, which are connected to breast cancer risk." (PMID 38711004, 2024). "Deleterious BRCA2 mutations have been observed in 4 to up to 14% of male breast cancers, whereas BRCA 1 mutations are rare, except in individuals of Ashkenazi Jewish ethnicity." (PMID 38472501, 2024). "While BRCA1 mutation carriers typically develop basal-like breast cancers, breast cancers in BRCA2 mutation carriers are much more heterogenous." (PMID 38059556, 2024). "In this study, we report the case of a patient with a BRCA2 mutation who developed both familial breast cancer and prostate cancer." (PMID 39364320, 2024). "BRCA1 and BRCA2 are the most common mutated genes seen in patients with ovarian and breast carcinomas." (PMID 38344545, 2024). "Male breast cancer (MBC) affects around 1 in 1000 men and is known to have a higher underlying component of high and moderate risk gene pathogenic variants (PVs) than female breast cancer, particularly in BRCA2." (PMID 38609177, 2024). "The NSABP-P1 breast cancer prevention trial showed that tamoxifen reduced the risk of developing BC by 62% in BRCA2-mutated carriers (RR = 0.38, 95% CI 0.06–1.56)." (PMID 38184581, 2024).
breast cancer (continued). "Germline pathogenic (or likely pathogenic) variants in BRCA genes are the primary genetic risk factors, with BRCA1 mainly associated with female breast cancer and BRCA2 with male breast cancer." (PMID 39272907, 2024). "Patients with a BRCA2 mutation exhibit a 26% likelihood of developing contralateral breast cancer (CBC) within 20 years following their initial BC diagnosis." (PMID 38184581, 2024). "Mutations in the BRCA1 and/or BRCA2 genes (BRCAm) increase the risk of developing breast cancer (BC) and are found in ~5% of unselected patients with the disease." (PMID 39215191, 2024). "ISG15 depletion significantly reduces cell proliferation rates in human BRCA1-mutated triple-negative, whereas its upregulation results in increased resistance to the chemotherapeutic drug cisplatin in mouse BRCA2-deficient breast cancer cells, respectively." (PMID 37783689, 2023). "Specific gene mutations, such as mutations in the BRCA1 and BRCA2 genes, significantly increase the risk of developing breast cancer." (PMID 37575755, 2023). "In 2020, modified segregation analyses performed in 524 breast cancer families with pathogenic variants in PALB2 confirmed that this gene confers a risk for breast cancer that is comparable to that of BRCA2." (PMID 37444426, 2023). "It was shown in BRCA2-mutated mouse mammary tumours that loss of PARG expression enables PARylation despite PARP inhibition, which can contribute to resistance." (PMID 37430137, 2023). "Two key factors associated with a high risk of breast cancer are mutations in the BRCA1 and BRCA2 (Breast Cancer; OMIM 113705 and OMIM 600185, respectively) genes, with the majority of hereditary cases attributed to the BRCA1 gene." (PMID 37147448, 2023). "A transfeminine patient with localized prostate cancer opted for orchiectomy for both gender affirmation and androgen deprivation therapy, and a trans man with BRCA2 mutated breast cancer chose bilateral mastectomy, hysterectomy, and salpingo-oophorectomy." (PMID 37746299, 2023). "Germline pathogenic variants in the BRCA1 and BRCA2 genes are associated with high risks of developing breast cancer." (PMID 37444426, 2023). "Her sister had a history of breast cancer in her 30s and was found to be a BRCA2 pathogenic variant carrier by genetic testing." (PMID 37957733, 2023). "A recent clinical trial demonstrated that breast cancer patients with germline mutations in BRCA1 or BRCA2 benefit from Poly(adenosine diphosphate–ribose) polymerase (PARP) inhibitor treatment." (PMID 37316882, 2023). "This study confirms previously published results of unfavorable breast cancer prognosis associated with ER+ tumors, especially Luminal A-like tumors, in young women as well as BRCA2-carriers." (PMID 38036573, 2023). "In a Lebanese study, fewer than 6% of patients with early onset or familial breast cancer carried a known BRCA1 or BRCA2 PV, suggesting that alternative variants drive breast cancer incidence in this population." (PMID 37306523, 2023). "For example, variants in PALB2 (Partner and Localizer of BRCA2) are associated with an estimated cumulative risk of breast cancer of 14%." (PMID 37182128, 2023). "A large prospective study found that women who inherit deleterious germline mutations of BRCA1 or BRCA2 have very high cumulative risks for developing breast cancer (e.g., risks to 80‐year‐olds are 72% and 69% for BRCA1 and BRCA2 carriers, respectively)." (PMID 35778884, 2023). "It is estimated that 40%-80% of carriers of BRCA1 and BRCA2 mutations have a probability of developing breast cancer and increased risk is also associated with family history." (PMID 37719058, 2023). "A matched case-control study included 1665 pairs of women with BRCA1 (n = 1243 pairs) and BRCA2 (n = 422 pairs) P/LP germline variants to assess the association between breastfeeding and breast cancer risk." (PMID 37628558, 2023).
breast cancer (continued). "Mutations in the BRCA1 and BRCA2 genes were shown to be associated with a risk of 60–85% of developing breast cancer." (PMID 37626804, 2023). "Our results suggest the breast cancer risk-modifying effect of the ALDH2-rs10744777 TT genotype among carriers of the BRCA2 p.K3326* mutation." (PMID 37943872, 2023). "The exclusion of breast cancer patients with a family history of breast cancer had a minor impact on PTV association with overall breast cancer risk (i.e., BRCA2 adjusted OR of 8.74; 1.57-48.75 95% CI, p-value = 0.013)." (PMID 37790698, 2023). "ISG15-mediated fork protection is beneficial to cancer cells; indeed, the sole upregulation of ISG15 increases resistance of BRCA2-deficient mouse breast cancer cells to platinum-derived chemotherapeutic agents." (PMID 37783689, 2023). "In this context, our study assessed breast cancer surveillance behaviors among a cohort of Sri Lankan women genetically predisposed to breast cancer with BRCA1 or BRCA2 pathogenic variants." (PMID 38017478, 2023). "Previously, we reported a loss of heterozygosity, which is one of the mechanisms of BRCA2 inactivation in mammary tumors." (PMID 36851449, 2023). "We illustrate the use of this method to calculate LRs for 24 BRCA1 and 68 BRCA2 variants from breast cancer case-control genotype data generated by the Breast Cancer Association Consortium (BCAC) as part of the large-scale OncoArray project." (PMID 38725546, 2023). "A mutation in the genes breast-cancer-1 (BRCA1) or breast-cancer-2 (BRCA2) is carried by 25% of patients with familial predisposition." (PMID 36765786, 2023). "Three of these genes are related to the DNA Interstrand Crosslink Repair: BRCA1 and BRCA2 are the quintessential breast cancer susceptibility genes." (PMID 37182128, 2023). "Individuals carrying BRCA1 or BRCA2 mutations have a higher lifetime risk of developing breast cancer and an increased risk of ovarian cancer." (PMID 37575755, 2023). "BRCA2, which is a tumor suppressor gene, was initially reported as a breast cancer susceptibility gene in 1995." (PMID 37943872, 2023). "In contrast, patients with BRCA2 mutations are mainly associated with estrogen receptor (ER)‐positive breast cancer." (PMID 35778884, 2023). "Here, to address this apparent contradiction, we combined genome-graph analysis of short-read whole-genome sequencing (WGS) profiles across thousands of tumours with deep linked-read WGS of 46 BRCA1- or BRCA2-mutant breast cancers." (PMID 37587346, 2023). "Mutations in the breast cancer susceptibility gene, BRCA2, greatly increase an individual’s lifetime risk of developing breast and ovarian cancers." (PMID 36976771, 2023). "BRCA1 and BRCA2 (known as BReast CAncer genes 1 and 2) are the most widely recognized breast cancer susceptibility genes." (PMID 37958392, 2023). "Likelihood ratios were calculated for a case-control dataset of BRCA1 and BRCA2 variants from the Breast Cancer Association Consortium (BCAC) and compared with logistic regression results." (PMID 38725546, 2023). "Mutations in BRCA1 and BRCA2 have not only been associated with an increased risk of breast cancer as they were later also found to increase susceptibility to ovarian, pancreatic, and prostate cancers." (PMID 37509303, 2023). "Especially in the Asian populations, gBRCA1/2-associated breast cancer are known to develop in younger age, with higher incidence of germline BRCA2 (gBRCA2) mutation than germline BRCA1 (gBRCA1) when compared to other ethnicities." (PMID 36604691, 2023). "In particular, BRCA2 seems to play a primary role as men with a BRCA2 mutation have a lifetime risk of developing breast cancer of about 5–10%." (PMID 37999136, 2023). "In breast cancer, BRCA2 germline mutations have been found to be significantly associated with brain metastasis, regardless of tumor subtype." (PMID 36980614, 2023).
breast cancer (continued). "Having observed this interaction in breast cancer, we aimed to investigate the association of the BRCA2 p.K3326* mutation with ESCC risk in the context of the ALDH2 rs10744777 variant." (PMID 37943872, 2023). "We obtained analogous results using the BRCA2-deficient (Brca2-/-) mouse mammary tumor cell line KB2P (clone 1.2129), confirming that treatment with IFNβ did not restore RAD51 foci." (PMID 37783689, 2023). "P/LP variants in BRCA1 confer a higher risk for breast cancer compared to P/LP variants in BRCA2 and RRM in women with asymptomatic BRCA1 P/LP variants has been shown to have improved survival compared to those who opted for IBS." (PMID 36971799, 2023). "Given the high lifetime risk of breast cancer (81–88%) in women carrying this mutation, a genetic analysis, including the detection of deleterious mutations to identify carriers of the BRCA2 mutation, is recommended." (PMID 36851449, 2023). "By lowering BRCA1’s ability to repair DNA, the high expression of RING domain-deficient BRCA1 proteins in breast cancer cell lines increases resistance to cisplatin and PARPi, while deletion mutations in BRCA2 would result in resistance to PARPi." (PMID 37476378, 2023). "Although mutations of the BRCA1 and BRCA2 genes can cause hereditary cancers, they are extremely rare in sporadic breast cancers." (PMID 37509303, 2023). "Altered BRCA2 carriers have a 5–10% lifetime breast cancer risk, 15–61% risk of PC, 3–5% risk of pancreatic cancer, and 3–5% risk of melanoma." (PMID 37347260, 2023). "Women with a pathogenic BRCA1 or BRCA2 variant had an increased risk of breast cancer that was higher in those with a first-degree family history (relative hazard 10.3 and 7.8, respectively) than those without (7.2 and 4.7)." (PMID 37936660, 2023). "It has been reported that Olaparib is an oral poly (ADP-ribose) polymerase inhibitor with activity in germline BRCA1 and BRCA2 (BRCA1/2)-associated breast cancers." (PMID 36906594, 2023). "Further, it has shown that BRCA1 and BRCA2 genetic mutations identified are of clinical relevance and there is a need to screen for these mutations in breast cancer patients to understand their implication in patient management outcomes." (PMID 37719058, 2023). "SNORA68 is a small nucleolar RNA (snoRNA) located at p13.1 on chromosome 19 (19p13.1) that is associated with susceptibility to ovarian and breast cancer in individuals with BRCA1 or BRCA2 mutation." (PMID 38053181, 2023). "Here, we use breast cancer variants affecting different domains of BRCA2 to shed light on this function." (PMID 36707518, 2023). "Breast cancer 2, early onset (BRCA2) malignant mutations are associated with tumorigenesis in humans and dogs." (PMID 36851449, 2023). "In the case of genetic predisposition, such as a mutation within the BRCA1 and BRCA2 genes, the relevance of hormones in breast cancer development increases significantly." (PMID 36983412, 2023). "In carriers of mutations in the BRCA1 and BRCA2 genes, the risk of developing breast cancer increases to even 80%." (PMID 37108398, 2023). "Two components of the FA signaling pathway, namely BRCA1 and BRCA2, function as susceptibility genes for breast cancer." (PMID 38025539, 2023). "A limited fraction of high-risk familial non-BRCA1/BRCA2 breast cancer patients is expected to benefit from treatment strategies against homologue repair deficient cancer cells." (PMID 37316882, 2023). "Various resistance mechanisms, other than BRCA1/BRCA2 reversion mutations, have been reported in ovarian and breast cancer; however, there have been few reports on prostate cancer." (PMID 37174127, 2023). "Breast cancer 2, early onset (BRCA2) mutations are associated with tumorigenesis in humans and dogs." (PMID 36851449, 2023). "Examples include the BRCA1 and BRCA2 genes, which are associated with an increased risk of breast cancer." (PMID 38384741, 2023).